DBH-AS1 (DBH antisense RNA 1)
Synonyms: BPR; NCRNA00118
Gene: Long non-coding RNA gene on chromosome 9 (133,654,586 to 133,657,313, reverse strand). Ensembl gene ENSG00000225756.
Diseases named in the same sentence as DBH-AS1 in open-access papers:
DBH-AS1 is named in the same sentence as 1 disease in open-access papers, as found by Europe PMC text mining. Sharing a sentence is not in itself a finding about the gene and the disease. The quoted sentences say what the papers report.
cancer (1 paper, 2025). A tumor composed of atypical neoplastic, often pleomorphic cells that invade other tissues. "DBH‐AS1 is upregulated by METTL3‐mediated m6A modification, and overexpression of DBH‐AS1 sponges miR‐3163 and upregulates the expression of USP44, a target gene of miR‐3163, thereby reducing gemcitabine resistance and suppressing cancer growth." (PMID 40448344, 2025).